RGCC (regulator of cell cycle)
Description:
Modulates the activity of cell cycle-specific kinases. Enhances CDK1 activity. May contribute to the regulation of the cell cycle. May inhibit growth of glioma cells by promoting arrest of mitotic progression at the G2/M transition. Fibrogenic factor contributing to the pathogenesis of renal fibrosis through fibroblast activation.
Synonyms: RGC-32; C13orf15; RGC32; bA157L14.2
Tractability: PROTAC: its protein half-life has been measured.
Gene: Protein-coding gene on chromosome 13 (41,457,532 to 41,470,877, forward strand). Ensembl gene ENSG00000102760.
Subcellular location: Cytoplasm; Nucleus; Cytoplasm, cytoskeleton, microtubule organizing center, centrosome
Subcellular location (Human Protein Atlas): Nucleoplasm; Nucleoli
Gene Ontology:
Molecular function: protein binding; protein kinase activator activity; protein kinase binding; protein kinase regulator activity; R-SMAD binding; kinase activator activity
Biological process: cellular response to hypoxia; complement receptor mediated signaling pathway; negative regulation of angiogenesis; negative regulation of blood vessel endothelial cell migration; negative regulation of cell population proliferation; negative regulation of cell-cell adhesion mediated by cadherin; negative regulation of cytokine production; negative regulation of endothelial cell proliferation; negative regulation of exit from mitosis; negative regulation of fibroblast growth factor production; negative regulation of mitotic cell cycle phase transition; phosphatidylinositol 3-kinase/protein kinase B signal transduction; positive regulation of collagen biosynthetic process; positive regulation of cytokine production; positive regulation of endothelial cell apoptotic process; positive regulation of epithelial to mesenchymal transition; positive regulation of extracellular matrix assembly; positive regulation of extracellular matrix constituent secretion; positive regulation of G1/S transition of mitotic cell cycle; positive regulation of gene expression; positive regulation of stress fiber assembly; positive regulation of transcription by RNA polymerase II; positive regulation of vascular associated smooth muscle cell proliferation; transforming growth factor beta receptor signaling pathway; fibroblast activation; and 2 more
Cellular component: centrosome; cytoplasm; nucleolus; nucleoplasm; nucleus; cytosol
Genetic constraint (gnomAD): Loss-of-function variants: 14 observed, 6.83 expected, observed/expected ratio (o/e) 2.05. That is too few expected variants to judge how well the gene tolerates losing a copy. Missense variants: 156 observed, 129.04 expected, observed/expected ratio (o/e) 1.21, 90% interval 1.06 to 1.38. Synonymous variants: 72 observed, 55.11 expected, observed/expected ratio (o/e) 1.31, 90% interval 1.08 to 1.59.
Homologues: Orthologues: chimpanzee RGCC (100% identical), macaque RGCC (95% identical), pig RGCC (94% identical), dog RGCC (93% identical), rat Rgccl1 (89% identical), guinea pig RGCC (88% identical), rat Rgccl1 (88% identical), mouse Rgcc (87% identical), tropical clawed frog rgcc (62% identical), zebrafish rgcc (61% identical).
Diseases named in the same sentence as RGCC in open-access papers:
RGCC is named in the same sentence as 70 diseases in open-access papers, as found by Europe PMC text mining. Sharing a sentence is not in itself a finding about the gene and the disease. The quoted sentences say what the papers report.
breast carcinoma (5 papers, 2016 to 2025). "Taken together, these data show that the increased expression level of RGCC is associated with breast cancer lung metastasis and poor prognosis in TNBC." (PMID 38102722, 2023). "In human breast cancer cell lines, C5a induces the overexpression of the RGCC gene (response gene to complement 32 protein, involved in cell cycle progression), by activating the Akt pathway." (PMID 40370471, 2025). "In conclusion, our findings show that the combination of carboplatin, paclitaxel, and RGCC inhibition can act synergistically to suppress breast cancer lung metastasis, which could bring therapeutic benefits for TNBC patients with lung metastasis." (PMID 38102722, 2023). "Similarly, the RGCC protein was overexpressed in breast cancer lung metastases of compared with primary tumor tissues." (PMID 38102722, 2023). "Further analysis of the breast cancer cohort data in the Gene Expression Omnibus (GEO) revealed that the high expression level of RGCC was closely related with lung metastasis, but not metastasis to other organs." (PMID 38102722, 2023).
pancreatic cancer (4 papers, 2012 to 2024). "Interestingly, the increased RGCC expression was also found in lung metastases of multiple solid tumors, such as colorectal cancer, osteosarcoma, pancreatic cancer and prostate cancer." (PMID 38102722, 2023).
lung carcinoma (3 papers, 2018 to 2022). "RGCC was also shown to be downregulated in lung cancer patients according to the differential gene expression analysis of three different datasets; GSE18842, GSE19188, and GSE27262." (PMID 36067196, 2022).
bladder cancer (2 papers, 2021 to 2024). "It was found that regulators of cell cycle and cell proliferation such as S100A4, CCND2, C13ORF15 (RGCC), and SYK and genes associated with glucose or ion transport such as SLC2A3 and TMEM16A (ANO1) were upregulated in the persistently infected bladder cancer cells." (PMID 34044804, 2021).
glioblastoma (2 papers, 2011 to 2025). The most malignant astrocytic tumor (WHO grade IV). "For example, RGCC, SPP1 (osteopontin), GPNMB, and APOE are highly expressed in hepatocellular carcinoma (HCC), whereas PLVAP (PV1), CD276 (B7-H3), and ESM1 are predominantly expressed in glioblastoma (GBM)." (PMID 41303611, 2025).
hepatocellular carcinoma (2 papers, 2024 to 2025). A malignant tumor that arises from hepatocytes. "utilized bioinformatics and network pharmacology to identify that the regulator of cell cycle gene (RGCC) and atypical chemokine receptor 3 (ACKR3) are implicated in the progression from non-alcoholic liver disease to hepatocellular carcinoma and impact the prognosis of hepatocellular carcinoma." (PMID 39206194, 2024).
leukemia (2 papers, 2019 to 2025). A malignant (clonal) hematologic disorder, involving hematopoietic stem cells and characterized by the presence of primitive or atypical myeloid or lymphoid cells in the bone marrow and the blood. "The RGCC protein, a regulator of the cell cycle and a potential contributor to leukemia, was also targeted by IgG from both HAM/TSP and ATLL patients." (PMID 41303346, 2025). "Approximately 300 upregulated genes, including RGCC and JARID2 during TPA-mediated leukemia cell differentiation were obtained." (PMID 31700696, 2019).
lung adenocarcinoma (2 papers, 2022 to 2023). A carcinoma that arises from the lung and is characterized by the presence of malignant glandular epithelial cells. "In lung adenocarcinoma (LUAD), RGCC stimulates epithelial-mesenchymal transition (EMT), enhances cell migration and invasion, and reduces MMP-2 and MMP-9 protein activity and expression." (PMID 37576389, 2023).
multiple myeloma (2 papers, 2011 to 2022). "RGCC behaves as putative oncosuppressor in pediatric B-ALL, multiple myeloma, and other tumor types, where it was found to be epigenetically silenced." (PMID 35974102, 2022).
AIDS (1 paper, 2022). A syndrome resulting from the acquired deficiency of cellular immunity caused by the human immunodeficiency virus (HIV). "We screened four immune cell-related genes, ARRB1, DPEP2, LTBP3, and RGCC, which may be considered as the diagnostic markers for HIV-1/AIDS." (PMID 36123690, 2022).
hepatitis B (1 paper, 2024). "We also examined FOSB, GPAT3, RGCC, and RNF43 expression in patients with hepatitis B, hepatitis C, and AIH." (PMID 38965537, 2024). "We also detected the expression of FOSB, GPAT3, RGCC, and RNF43 in the blood of patients with hepatitis B, hepatitis C and AIH." (PMID 38965537, 2024). "The results showed an increased expression of FOSB in patients with hepatitis B, an increased expression of RNF43 in patients with hepatitis C, and an increased expression of RNF43 along with a decreased expression of RGCC in patients with AIH." (PMID 38965537, 2024).
HIV-1 infection (1 paper, 2022). The type species of lentivirus and the etiologic agent of acquired immunodeficiency syndrome (AIDS). "As the best model for diagnosing HIV-1±, RF was used to select four critical immune cell-related genes, namely, ARRB1, DPEP2, LTBP3, and RGCC, and a nomogram model was created to predict the occurrence of HIV-1 infection based on four key immune cell-related genes." (PMID 36123690, 2022). "These genes, including ARRB1 and RGCC, were shown to be involved in the regulation of immune-related biological processes, which is consistent with the classical process required for HIV-1+, suggesting a potential mechanism of HIV-1 infection." (PMID 36123690, 2022). "In addition, RGCC was shown to be involved in the negative regulation of fibroblast growth factor synthesis, and both RGCC and LTBP3 have been connected to the regulation of extracellular matrix formation (GO: 0,085,029) during HIV-1 infection." (PMID 36123690, 2022).
psoriasis (1 paper, 2022). An autoimmune condition characterized by red, well-delineated plaques with silvery scales that are usually on the extensor surfaces and scalp. "The level of RGCC (the gene encoding RGC-32) mRNA was significantly lower in lesional psoriasis than in samples from normal individuals." (PMID 35837394, 2022).
pulmonary hypertension (1 paper, 2014). Increased pressure within the pulmonary circulation due to lung or heart disorder. "These genes, such as PLA2G12A, RGCC, C9ORF3, GRIN2B, GRID1 and EPAS1, are involved in high-altitude physiology including angiogenesis, pulmonary hypertension, oxygen intake, defense response and erythropoiesis." (PMID 25270331, 2014).
squamous cell carcinoma (1 paper, 2021). A carcinoma arising from squamous epithelial cells. "Esophageal squamous cell carcinoma cells (ESCC9706) also displayed a modest increase in RGCC mRNA expression; however, RGCC regulation did not occur in tongue squamous carcinoma cells (SCC9) or in HeLa cells." (PMID 34015051, 2021).
tumor (25 papers, 2011 to 2025). "These imply that the upregulated RGCC is a common molecular event for multiple tumor types’ lung metastases, and may work as a diagnostic marker of pulmonary metastasis in patients with cancers." (PMID 38102722, 2023). "The anomalous expression of RGCC has been observed in a variety of primary tumors, either enhancing or preventing the growth of tumors, due in part to the signaling context in tumor cells and the microenvironment." (PMID 38102722, 2023). "DEG analysis after chemotherapy showed only moderate transitions whilst tumor-associated DEGs included ACKR1, RGCC and TM4SF1." (PMID 36253784, 2022). "Tumor suppressor properties have also been observed for RGCC (regulator of cell cycle) also known as RGC-32 (response gene to complement) that is involved in the regulation of cell cycle progression." (PMID 35386334, 2022). "In addition, RGCC knockdown cells or tumor cells treated with Volasertib, Dorsomorphin, or etomoxir (a fatty acid oxidation inhibitor) had a reduced NADPH/NADP + ratio and increased ROS levels." (PMID 38102722, 2023). "Of note, the functional role of RGCC in tumor metastasis has been scarcely reported." (PMID 38102722, 2023). "Collectively, RGCC/PLK1/AMPKα2 signal axis-mediated oxidative phosphorylation and fatty acid oxidation is critical for cell survival of disseminated tumor cells in lung, thereby facilitating pulmonary-tropic metastasis." (PMID 38102722, 2023). "Among the downregulated genes in LA-treated cells were RGCC, a cell cycle regulator; CYTOR, a long non-coding RNA that enhances proliferation; and CEACAM6, which is a cell adhesion molecule that promotes tumor progression." (PMID 33546321, 2021).
cancer (14 papers, 2011 to 2025). A tumor composed of atypical neoplastic, often pleomorphic cells that invade other tissues. "Initially, qRT-PCR analysis confirmed the RNA interference by siRNA targeting CDK5RAP2, MAD1L1, and RGCC (p< 0.05) in the COAD-derived cancer cell lines of HCT116 and SW480." (PMID 38143740, 2023).
infection (5 papers, 2011 to 2021). The state of being infected such as from the introduction of a foreign agent such as serum, vaccine, antigenic substance or organism. "Nevertheless, the infection was also able to repress cell cycle related genes, such as cyclin G1 (CCNG1), regulator of cell cycle (RGCC), and synaptonemal complex protein 3 (SYCP3)." (PMID 27197554, 2016). "In up-regulated genes of head kidney samples, 2 genes respond to infection by D. pseudospathaceum-clone I (HYAL2, PRF1), 3 to clone XII (RGCC, CYP27B1, CCR9) and 6 to the clone mix treatment (ITGA5, SIX1, ATP1B3, MEF2C, MLF1, MYLPF)." (PMID 25254967, 2014).
bacterial infections (1 paper, 2022). "Comparison of these results with those obtained from bacterial infections showed genes associated with cell‐cycle progression and cell proliferation (RGCC, SENP5, SMC6, SERTAD3, MAD2L1BP) to be specifically upregulated in DC3s." (PMID 34333764, 2022).
myopathy (1 paper, 2024). A disease of the muscle in which the muscle fibers do not function properly. "The TDH and RGCC genes were upregulated in the PMM of WS-affected chickens and, although not involved in the BPs identified in this study, were related to WS for the first time, establishing them as key functional candidates for myopathy development." (PMID 39199913, 2024).
RGCC also shares sentences with these, for which no sentence is quoted: colon carcinoma (8 papers); glioma (4); atherosclerosis (3); experimental autoimmune encephalomyelitis (3); adenocarcinoma (2); adenoma (2); colon adenocarcinoma (2); colorectal cancer (2); COVID-19 (2); IgA nephropathy (2); lung fibrosis (2); lymphoma (2); metabolic disease (2); non-small cell lung carcinoma (2); Obesity (2); prostate carcinoma (2); acute coronary syndrome (1); adrenocortical carcinoma (1); asthma (1); astrocytoma (1); autoimmune disease (1); Autoimmunity (1); breast tumors (1); Burkitt lymphoma (1); cardiac disease (1); chronic pancreatitis (1); diffuse large B-cell lymphoma (1); dilated cardiomyopathy (1); Fanconi anemia (1); heart failure (1).
A further 20 diseases each share a sentence with RGCC in 1 paper.